CD163 (CD163 molecule)
Diseases named in the same sentence as CD163 in open-access papers (continued):
Sharing a sentence is not in itself a finding about the gene and the disease.
non-small cell lung carcinoma (12 papers, 2010 to 2023). A group of at least three distinct histological types of lung cancer, including non-small cell squamous cell carcinoma, adenocarcinoma, and large cell carcinoma. "Soluble CD163 was found to be a potential diagnostic parameter for monitoring the presence of macrophages, both in human biopsies of non-small cell lung cancer (NSCLC) and human esophageal squamous cell carcinoma line." (PMID 34041037, 2021). "Quite recently, CD163+ TAM infiltration inversely correlated with overall survival in non-small cell lung cancer (NSCLC) patients undergoing immune checkpoint blockers treatment." (PMID 36359283, 2022). "In non-small cell lung cancer, SUVmax was correlated with CD8(+) TILs as well as CD163(+) tumor-associated macrophages, FoxP3(+) Treg cells, and PD-1(+) and PD-L1(+) cells." (PMID 34103577, 2021). "This study demonstrates that the tumor-associated macrophages in non-small cell lung cancer contain two distinct forms, a CD68+/HLA-DR+ M1 form and a CD68+/CD163+ M2 form." (PMID 20338029, 2010). "In a recent publication, the therapeutic effect of checkpoint inhibitor therapy could even be predicted by observing the levels of CD8/CD68/CD163/PD-L1 positive cells in non-small cell lung cancer." (PMID 36576530, 2023). "Furthermore, increased myelomonocytic markers like CD14 and CD163 were detected after macrophage differentiation by soluble mediators of non-small cell lung carcinoma cell lines." (PMID 25902944, 2015). "Further, lymphangiogenesis and angiogenesis are promoted by M2-like (high ratio of CD163+/CD68+) TAMs, whereby a high expression of VEGF-C and VEGF-A by M2-like macrophages was reported in patients with non-small-cell lung cancer (NSCLC)." (PMID 37958332, 2023).
pneumonia (12 papers, 2009 to 2025). An acute, acute and chronic, or chronic inflammation focally or diffusely affecting the lung parenchyma, caused by an infection in one or both of the lungs (by bacteria, viruses, fungi, or mycoplasma.). "The activation of CD68+/CD163+ macrophages could cause cell damage at an early stage of pneumonia development, and subsequently cause fibrotic changes in lung tissue." (PMID 37109672, 2023). "Although statistically significant correlations were not recorded, it is noteworthy that patients with pneumonia/bronchopneumonia-associated lesions recorded higher CD163 values compared to cases without this diagnosis (mean value 38.75% vs. 28.89%) (p = 0.196)." (PMID 39202593, 2024). "Our study has some limitations; we studied a selected group of patients (with symptoms and signs of meningitis or pneumonia), we measured the markers at one time point only, and we did not investigate the membrane-bound components of CD163 or TREM-1." (PMID 19675669, 2009).
encephalitis (11 papers, 2010 to 2024). An acute inflammatory process affecting the brain parenchyma. "This is based on the fact that monocyte turnover from bone marrow likely correlates with the development of end organ disease such as encephalitis and pneumonitis and occurs with signs of global activation in plasma typified by levels of CD163 and the actual size of the viral reservoir." (PMID 28279181, 2017). "In brief, the infected macaques that developed both SIV-related encephalitis and CVD had higher levels of plasma sCD163 and IL-18 and had a higher proportion of cardiac macrophages (CD68+, CD163+, CD206+, and MAC387+)." (PMID 38781301, 2024). "In SIV encephalitis, productively infected CD14 + CD16 + CD163 + CD45hi perivascular macrophages are abundant." (PMID 25852823, 2015). "In contrast, in chronic lesions CD68 + CD163+ macs are most highly represented in SIV-infected animals and in HIV-infected human with encephalitis." (PMID 25852823, 2015). "Although microglial expression of CD163 is seen in the parenchymal white matter in SIV infection without encephalitis, it does appear to be greater in SIVE." (PMID 25886134, 2015). "A marker that correlates with the number of BrdU+ monocytes in these animals is soluble CD163 (sCD163) in plasma, and it was shown that significantly higher levels of sCD163 were present in the plasma of SIV-infected macaques that develop encephalitis compared to macaques that do not." (PMID 34451482, 2021). "In neuroinflammatory conditions, CD163+ macrophages infiltrate into brain tissue, including in encephalitis [both human immunodeficiency viral and simian immunodeficiency viral (HIV and SIV) encephalitis], multiple sclerosis (MS), Parkinson's disease (PD), and Alzheimer's disease (AD)." (PMID 33133060, 2020). "Likewise, a slight accumulation of CD163+ perivascular MΦs is seen in SIV-infected animals without encephalitis, as compared to non-infected animals, but without the significant cuffing characteristic of SIVE." (PMID 25886134, 2015). "This reveals an overall marked accumulation of CD163+ MΦs and microglia in SIVE, as compared to the SIV without encephalitis and non-infected groupings." (PMID 25886134, 2015).
esophageal cancer (11 papers, 2014 to 2025). A primary or metastatic malignant neoplasm involving the esophagus. "In esophageal cancer, the high infiltration of CD163+ macrophages is significantly associated with chemoresistance." (PMID 34362423, 2021). "In patients with esophageal carcinoma, a high density of CD163+ TAMs, which is also associated with significantly increased PD-L1 expression, was associated with significantly worse OS than a low density (log-rank P = 0.0025)." (PMID 31417907, 2019). "The results showed that compared with healthy controls, the expression of CD163, a marker of M2 macrophages, was significantly increased in esophageal cancer tissues." (PMID 35646112, 2022). "In esophageal cancer patients, cases with high CD163 and CD204 expression levels showed a significantly shorter overall survival than those with comparatively lower CD163 and CD204 levels." (PMID 33463063, 2021). "In our study, the number of CD163+ M2 correlated with a good prognosis of esophageal cancer (HR = 0.4447, p = 0.0456∗)." (PMID 32884895, 2020). "The importance of the ITGB2 pathway in MΦ function is emphasized by a positive correlation between ITGB2 expression and CD163+ MΦ infiltration in esophageal carcinoma where scRNA-seq analysis indicated a progressive increase in ITGB2 with the acquisition of a tumor-promoting phenotype." (PMID 40432828, 2025). "Higher CD163+ TAMs infiltration in the stroma compared to the tumor parenchyma was also reported in esophageal carcinoma where it correlated with worse OS, but an impact of elevated CD163+ TAMs infiltration on tumor aggressiveness was observed in both compartments." (PMID 33807310, 2021). "That report suggested that a high density of PD-L1-expressing CD163+ TAMs could offer a prognostic biomarker for esophageal carcinoma." (PMID 31417907, 2019). "Expression of CD68/CD163 in esophageal cancer tissues and adjacent tissue." (PMID 25144454, 2014). "Furthermore, different prognostic values of CD163+ cells in different types of tumor of the same localization indicate that it can be strongly affected by specific tumor features that remain to be elucidated for esophageal cancer." (PMID 32884895, 2020).
glomerulonephritis (11 papers, 2020 to 2025). A renal disorder characterized by damage in the glomeruli. "Elevated CD163 levels have been observed in several chronic kidney diseases, including glomerulonephritis and proteinuric nephropathies." (PMID 40969366, 2025). "In ANCA glomerulonephritis, urinary CD11b+ and CD163+ correlated with leukocyte recruitment in the kidney." (PMID 34307414, 2021). "Urine-soluble CD163 (usCD163) is released from alternatively activated macrophages involved in the resolution of inflammation in glomeruli and plays an important role in glomerulonephritis." (PMID 35911758, 2022). "Additionally, CD163 was found mainly expressed in active crescentic glomerulonephritis, proliferative glomerular lesions and areas of tubulointerstitial injury." (PMID 32351512, 2020). "Importantly, CD163+/CD68+ macrophages may be involved in the pathogenesis of proliferative glomerular crescents, such as in ANCA-associated glomerulonephritis or active LN." (PMID 34307414, 2021). "Glomerulonephritis samples additionally showed expression of collagen (COL1A1) and immune cell markers for monocytes or macrophages (LYZ and CD163) and T cells (CD3D, CD3E and CD3G)." (PMID 41028563, 2025).
Hemophagocytosis (11 papers, 2010 to 2024). Phagocytosis by macrophages of erythrocytes, leukocytes, platelets, and their precursors in bone marrow and other tissues. "Furthermore, bone marrow biopsy showed foci of necrosis with associated acid-fast bacilli and hemophagocytosis highlighted by CD163 stain; consequently, secondary HLH was suggested." (PMID 35127182, 2022). "The diagnosis was confirmed by the laboratory findings of elevated CD163 and IL-2, as well as hemophagocytosis identified in a bone marrow biopsy." (PMID 34795304, 2021). "The aim of their study was to evaluate if hemophagocytosis was detectable through immunohistochemistry (staining for CD163) and so, in addition to the lung tissue, they also sampled the mediastinal and pulmonary hilar lymph nodes, liver, spleen, and bone marrow." (PMID 33026628, 2021). "Histopathology often reveals characteristic increased hemophagocytic activity in the bone marrow, liver, and spleen with positive CD163 (histiocyte) staining, although hemophagocytosis may not be present in initial stages and is neither sensitive nor specific for MAS." (PMID 30774631, 2019).
idiopathic pulmonary fibrosis (11 papers, 2018 to 2025). Idiopathic pulmonary fibrosis (IPF) is a nonneoplastic pulmonary disease that is characterized by the formation of scar tissue within the lungs in the absence of any known cause. "In lung samples from human idiopathic pulmonary fibrosis (IPF) patients, S100A4-positive macrophages co-express CD163, another M2-like macrophage marker, suggesting S100A4 expression is in M2-like macrophages." (PMID 40078995, 2025).
pancreatic ductal adenocarcinoma (11 papers, 2019 to 2025). An infiltrating adenocarcinoma that arises from the epithelial cells of the pancreas. "The objective of this study was to evaluate the diagnostic and prognostic potential of soluble CD163 (sCD163) in patients with pancreatic ductal adenocarcinoma (PDAC)." (PMID 36765852, 2023). "Monocytes co-cultured with CAFs from pancreatic ductal adenocarcinoma have been shown to present with increased surface expression of specific M2-markers, e.g., CD163, CD200R, and CD206 surface receptors and up-regulation of ARG1, IL10, and TGFB1 genes." (PMID 31108906, 2019). "For example, in pancreatic ductal adenocarcinoma, the knockdown of CCCTC-binding factor (CTCF) resulted in the downregulation of specific biomarkers of M2-like tumor-associated macrophages (TAMs), such as Mrc1 and CD163, reducing invasion and metastasis capabilities." (PMID 39033109, 2024). "Penny and colleagues also reported that pancreatic ductal adenocarcinoma produced TAMs expressing both M1 (IL‐1β, IL6, and TNF‐α) and M2 (CD163, CD206, and Arg1) markers." (PMID 37688511, 2023). "Indeed, Penny and colleagues also reported that pancreatic ductal adenocarcinoma-generated TAMs expressed both M1 (IL-1β, IL6, and TNF-α) and M2 (CD163, CD206 and Arg1) markers." (PMID 30927925, 2019).
renal cell carcinoma (11 papers, 2016 to 2025). "TCM from the renal cell carcinoma cell line 786-O also increased CD206 (p = 0.0028) & CD163 (p = 0.0109)." (PMID 41309950, 2025). "Soluble levels of PD-L1, IL-10, and CD163 have been reported as potential biomarkers in various cancers, although the prognostic value in renal cell carcinoma (RCC) has to be further elucidated." (PMID 35204426, 2022). "Consistent with our findings, PD-1 and CD163 correlation as checkpoint markers was found in renal cell carcinoma." (PMID 32756500, 2020). "Interestingly, in renal cell carcinoma higher CRP was associated with a stronger infiltration with CD8+, FoxP3+ and CD163+ cells and subsequently with worse prognosis." (PMID 31788452, 2019). "Soluble CD163, CXCL5, and blood cell counts, including absolute lymphocyte and eosinophil counts, were identified as predictors of irAEs in melanoma, renal cell carcinoma (RCC), and urothelial carcinoma." (PMID 41239350, 2025). "In the case of renal cell carcinoma, 17 TAM subsets have been characterized, most of them expressing CD169 while being discriminated by expression of CD163, CD204 and CD206." (PMID 31766350, 2019). "Paired CyTOF-based analyses of CD8 TILs and TAM in human renal cell carcinomas showed some correlation between exhausted CD8 TILs, CD4 regulatory T cells and a few peculiar TAM subpopulations (either CD169- CD163- CD68hi CD38hi CD204+; or CD169+ CD163+ CD68hi CD38hi CD204+ CD206+)." (PMID 31766350, 2019). "Patients with renal cell carcinoma treated with neoadjuvant bevacizumab demonstrated reduced CD31+ MVD and a reduced number of total CD68+, but not CD163+ TAMs in comparison with untreated patients." (PMID 34209679, 2021).
Alzheimer disease (10 papers, 2015 to 2025). A progressive, neurodegenerative disease characterized by loss of function and death of nerve cells in several areas of the brain leading to loss of cognitive function such as memory and language. "In AlzData database, the levels of CD44, CD93, and CD163 in patients with Alzheimer’s disease (AD) were significantly increased than those in normal controls." (PMID 35356296, 2022).
chronic kidney disease (10 papers, 2012 to 2025). Impairment of the renal function secondary to chronic kidney damage persisting for three or more months. "CD163-Hb scavenger receptors play an important role in the process of clearance and conversion of hemoglobin/heme in chronic kidney disease." (PMID 23013330, 2012). "Previous studies have found that CD163+ and CD206+ cells can promote matrix proliferation and interstitial fibrosis in chronic kidney disease, and M2 macrophages are associated with the formation of crescents in IgA nephropathy and the chronicity of the disease." (PMID 40799649, 2025). "Although a direct causal relationship between CD163+ macrophages and progressive fibrosis or a transition to chronic kidney disease (CKD) is not clear from this study, the important role of M2 macrophages in the transition from AKI to CKD has been demonstrated in several animal models." (PMID 32034190, 2020).
chronic viral hepatitis (10 papers, 2015 to 2025). "Increased CD163 expression on macrophages has been reported during viral hepatitis, and infection of pigs with porcine reproductive and respiratory syndrome virus and African swine fever virus." (PMID 33679766, 2021). "In the HCV-negative cohort (n = 103): CD68/CD163 ratio maintained significant predictive value for thrombosis (OR = 1.64, 95% CI:1.119–2.404, p = 0.011) in the HCV-negative cohort, confirming the robustness of our findings independent of viral hepatitis status." (PMID 41239536, 2025).
gastric adenocarcinoma (10 papers, 2019 to 2026). "The infiltration of CD68+/CD163- macrophages has been identified as a poor prognostic factor following neoadjuvant chemotherapy in EC and gastric adenocarcinoma." (PMID 40746552, 2025). "This study evaluated the prognostic significance of CD163+ M2 TAMs and MVD at the invasive front of gastric adenocarcinoma." (PMID 41899509, 2026).
Hodgkins lymphoma (10 papers, 2012 to 2025). A heterogeneous group of malignant lymphoid neoplasms of B-cell origin characterized histologically by the presence of Hodgkin and Reed-Sternberg (HRS) cells in the vast majority of cases. "We do acknowledge there is generally not an ideal marker for the tissue identification of subsets of macrophages, however, as compared with the commonly used antibody to CD68 (KP-1), CD163 appears to be a better marker for enumeration of tumor associated macrophages classical Hodgkin lymphoma." (PMID 22289504, 2012). "We tested 44 cases of classical Hodgkin lymphoma for antibodies to both CD68 and CD163 to determine if CD163 may be a better macrophage marker to enumerate tumor associated macrophages in classical Hodgkin lymphoma." (PMID 22289504, 2012). "The shed form of CD163 is upregulated in a large range of inflammatory diseases and Hodgkin lymphoma, is induced by anti-inflammatory factors such as IL-6 and IL-10, and is known to be upregulated in PCNSL." (PMID 29299134, 2017). "After analyzing 44 cases of classical Hodgkin lymphoma, CD163 showed lower staining levels than CD68 in HRS rich areas." (PMID 22289504, 2012). "We used immunohistochemical staining for the macrophage/monocyte markers CD68 and CD163 to directly compare the staining characteristics in 44 cases of classical Hodgkin lymphoma." (PMID 22289504, 2012). "We examined 44 cases of CHL, mostly nodular sclerosis subtype, in which the immunohistochemical stains for the histiocytic markers CD68 and CD163 were performed." (PMID 22289504, 2012). "In the group of patients presenting a nodular sclerosis subtype, the immune profile switched at relapse, with an upregulation of LGALS1 and TGFB1 and downregulation of CD163, CD274, HGF, IL15, and ICOS." (PMID 36230815, 2022). "Our previous study of classical Hodgkin lymphoma already indicated that CD163 may not be a specific marker for M2 polarization since the numbers of CD163+ macrophages were higher in tumour microenvironment of cases with a cytotoxic/Th1 signature." (PMID 24260507, 2013).